KCNK9 (potassium two pore domain channel subfamily K member 9)
Diseases named in the same sentence as KCNK9 in open-access papers (continued):
Sharing a sentence is not in itself a finding about the gene and the disease.
A further 28 diseases each share a sentence with KCNK9 in 1 paper.